BRAF (B-Raf proto-oncogene, serine/threonine kinase)
Diseases named in the same sentence as BRAF in open-access papers (continued):
Sharing a sentence is not in itself a finding about the gene and the disease.
melanoma (continued). "This suggests that blocking EMT-inducing pathways to abrogate invasion and/or metastasis might be an efficacious approach to complement modern melanoma therapies directed against cell proliferation (BRAF- and/or MEK-inhibition) or stimulation of the immune system by checkpoint inhibitor blockade." (PMID 29716947, 2018). "Interestingly, we found that AgGom and HiGom are also highly cytotoxic to two BRAF wild-type cells (C001 and C002), suggesting that these peptides might have anti-proliferative activities in a wide range of melanoma cell types." (PMID 30068931, 2018). "Together, these data show that BMP-2, nodal and their respective antagonists neither influence melanoma cell proliferation nor sensitize melanoma cells for the current standard treatment regimen for BRAF-mutated metastatic melanoma patients (BRAF±MEK-inhibition)." (PMID 29716947, 2018). "Importantly, we demonstrate that USP28 is deleted in a proportion of melanoma patients and may act as a biomarker for response to BRAF inhibitor therapy in patients." (PMID 29880484, 2018). "Furthermore, patient’s BRAF status is determined based on one tumour tissue sample, not uncommonly the (excised) primary melanoma, and consequently does not necessarily represent the mutational status of all metastases within a patient." (PMID 30460579, 2018). "The inactivation of p16CDKN2A is due to either genetic (mutations, deletions) or epigenetic (promoter methylation) mechanisms, whereas the amplification of CCND1 is particularly frequent in melanomas negative for BRAF/NRAS mutations, in chronically sun-exposed skin areas." (PMID 30218391, 2018). "In addition, high levels of miR-211 in melanoma-derived Exo were shown to indicate a reduced sensitivity to BRAF inhibitors, the mechanism of which involves the over-expression of MITF, a regulator of the TRPM1 gene, resulting in the prolonged survival of melanoma cells." (PMID 29755693, 2018). "Our findings suggest that a metformin/sitagliptin combination may contribute to treating melanoma with different driver mutations, including melanoma with or without a BRAF (V600E) mutation." (PMID 29899823, 2018). "p-ERK inhibition may play important roles in BRAF resistance in these two melanoma cell lines." (PMID 29929490, 2018). "Given the prominent role of the lymphocyte response to MAPK blockade in BRAF-mutated melanoma, these EMT-like shifts in melanoma cell state may well also contribute to BRAF inhibitor resistance at least in part by altering melanoma cell visibility via this antigenic shift." (PMID 29780391, 2018). "Similarly, loss of PTEN, a negative PI3K/AKT regulator and negative prognostic factor for melanoma, is associated with shorter progression free survival in BRAF inhibitor-treated patients but is not predictive of best overall response." (PMID 30237495, 2018). "Inhibition of p- ERK may play important roles in BRAF resistance in these two melanoma cell lines." (PMID 29929490, 2018). "Moreover, our proof-of-principle study focused on the driver mutations BRAF and NRAS, which account for up to 70% of melanomas, and are well suited to this purpose because of the low likelihood of clonal diversity with trunk mutations such as these in melanoma." (PMID 29112704, 2018). "Since RIP1-mediated NF-κB activation is mediated by its intermediate domain independently its kinase activity, inhibitors that specifically target the intermediate domain of RIP1 may be useful in improving the therapeutic efficacy of BRAF/MEK inhibitors in the treatment of melanoma." (PMID 29880840, 2018). "Although the outstanding results on patients give hopes that melanoma can be cured, achievement of prolonged survivals is hampered by the appearance of resistance mechanisms that may quickly develop and lead to relapse in patients treated with BRAF inhibitors." (PMID 29113311, 2017).
melanoma (continued). "It has been shown that mutations of proteins in the RAS/RAF/MAPK pathway promote glycolysis and the expression of cell surface glucose transporter 1 (GLUT1) in both colorectal cancer cell lines and in melanoma indicating that glucose metabolism might be important for BRAF-driven tumourigenesis." (PMID 28595656, 2017). "Furthermore, CD47 expression was upregulated by treatment with vemurafenib in a panel of fresh melanoma isolates carrying the BRAFV600E mutation.Taken together, these results suggest that treatment with BRAF or MEK inhibitors upregulates CD47 expression due to reactivation of ERK." (PMID 29050218, 2017). "In addition, mechanisms of primary treatment resistance of BRAF-mutant melanoma cells may be due to a MITF low/NF-κB high phenotype, which could be linked to a specific gene expression profile." (PMID 27903987, 2017). "For melanoma treated with BRAF inhibitors, resistance generally occurs within the first year and usually involves reactivation of the MAPK pathway by the acquisition of secondary NRAS or MEK mutations or alternative splicing or amplification of the BRAF gene itself." (PMID 28484715, 2017). "Alternatively, more reliable methods to measure the levels of growth factors released by melanoma cells and stromal cells in patients’ tumors might be developed to investigate their potential role in defining patients with poor response to BRAF/MEK inhibitor therapy." (PMID 28829835, 2017). "Five melanoma cell line pairs (A375, Mel1617, SKMel19, SKMel28, 451LU), consisting of a sensitive (S) and a secondary resistant (R) counterpart respectively, were used to assess the activation status of the p90 ribosomal S6 kinase and its relevance in BRAF inhibitor resistance." (PMID 28415756, 2017). "However, the results of BRAF IHC were very good although inferior to those obtained in melanomas." (PMID 28293477, 2017). "As demonstrated by the different efficacy of BRAF inhibitors in melanoma and colon cancer, the inclusion of multiple tumor types with the same molecular target in a basket trial might introduce an important source of heterogeneity and could lead to negative results." (PMID 28418920, 2017). "However, due to emergent resistance to single-agent RAFi in patients, combination treatments of BRAFi (dabrafenib) with MEKi (trametinib) have been developed for melanomas and are also being tested in pediatric patients with plexiform NF-1, BRAF-V600E refractory/relapsed tumors (NCT02124772)." (PMID 29156677, 2017). "Here, we could not only confirm that YB-1 is an important target of the MAPK/RSK signalling axis in malignant melanoma, but also show, that vemurafenib resistant melanoma cells can be re-sensitised towards long-term exposure with the BRAF inhibitor by YB-1 knockdown." (PMID 28415756, 2017). "The discovery of constitutive activity of the BRAF-MEK-ERK signalling pathway in melanomagenesis emphasizes the importance of these signalling pathway intermediates as potential therapeutic targets in treating melanoma especially those that have become resistant to BRAFV600E inhibitors." (PMID 28708099, 2017). "Therefore, the compensatory effects of RAF kinases is a conserved mechanism between human and murine NRAS-driven melanoma, since neither CRAF, nor BRAF loss alone is sufficient to block melanoma cell proliferation in both species." (PMID 28497782, 2017). "Besides, up to 20% melanoma patients with BRAF mutations do not respond to vemurafenib treatment at all, probably due to intrinsic resistance mechanisms such as amplification of tumor promoter genes or loss of tumor suppressor genes." (PMID 29299138, 2017). "Interestingly, inhibitors of other classes of kinases relevant to melanoma such as vemurafenib, which target mutated BRAF, did not synergize with fucoidan, suggesting this natural compound amplifies the effects of inhibitors that target ERBB3 signaling." (PMID 28060735, 2017).
melanoma (continued). "NICE guidance regarding eligibility for vemurafenib in BRAF V600 mutated melanoma stipulates that patients have metastatic disease, but not all patients tested met this criterion, accounting for some of the discrepancy between actionable mutations and subsequent changes to patient management." (PMID 28196074, 2017). "Finally, intrinsic resistance exists in a group of melanoma patients carrying BRAF mutations but not responding to BRAF and MEK inhibitors." (PMID 28595656, 2017). "As a result, while some melanoma cells may carry the V600E BRAF mutation, others, within the same patient, may carry different mutations not susceptible to BRAF inhibition." (PMID 29100459, 2017). "Additionally, 10% of melanomas previously classified as “BRAFWT” tumors actually harbor non-V600E/K mutations in BRAF." (PMID 28157711, 2017). "Furthermore, given the substantial diagnostic overlap between sporadic MPNST and the spindle-cell variant of melanoma, as well as the high frequency of BRAF V600 mutation in melanoma, we believe that any “BRAF V600 mutant MPNST” should be rigorously evaluated to exclude a misdiagnosis of melanoma." (PMID 29118384, 2017). "Moreover, these inhibitors were proven beneficial almost only in BRAF mutant melanomas, and thus a considerable number of melanoma patients remain without a targetable mutation." (PMID 29180761, 2017). "Nevertheless, IPI may still have a role as (i) a subsequent therapy in metastatic patients after progressive disease with anti-PD-1 and, if BRAF-mutant, BRAF/MEK inhibitors; (ii) an adjuvant therapy for high-risk stage III melanoma; and (iii) a combination therapy with anti-PD-1 drugs." (PMID 28446908, 2017). "Similarly, BRAF ctDNA testing of melanoma patients might also be used as pre-screening before attempting to obtain a result based on tissue samples." (PMID 28743309, 2017). "These treatments may be effective for melanoma regardless of the mutation status of BRAF or NRAS and may help overcome melanoma's resistance to current treatments." (PMID 27086916, 2017). "However, unlike BRAF-mutated melanoma, single-agent BRAF inhibition has been an ineffective strategy in BRAF-mutated colorectal cancer." (PMID 29312543, 2017). "Specifically, we have shown that ERBB3 is highly active (phosphorylated) in up to 70% of melanomas regardless of whether they carry mutated or wild type BRAF, the most common oncogenic driver in melanoma." (PMID 28060735, 2017). "BRAF is one of three mammalian RAF isoforms, and one that has the highest basal kinase activity and thus is the most common isoform mutated in human cancers that include melanoma but also hairy cell leukemia, papillary thyroid cancer and colorectal cancer (CRC)." (PMID 29276510, 2017). "In this manner, our melanoma mouse model is ideal for the study of tumor dormancy and resistance, both to BRAF and MEK inhibition, and is well suited to determine and validate additional genetic alterations found in recurrent tumors that may be responsible for resistance and regrowth." (PMID 28263969, 2017). "We have recently shown that up to 70% of melanomas, regardless of whether they possess mutated or wild type BRAF, show hyper-activation of ERBB3 and rely on an ERBB3/ERBB2 signaling cascade to promote cell survival." (PMID 28060735, 2017). "Intriguingly, while BRAF is mutated in up to 50% of melanoma, no CRAF mutation was found so far, suggesting that oncogenic CRAF activation may not be sufficient for tumour initiation." (PMID 28497782, 2017). "In addition to treating disseminated metastatic disease, BRAF/MEK inhibitors may also provide an effective neoadjuvant strategy for local or regional BRAFV600E mutant melanoma, allowing surgical removal of previously inoperable melanomas." (PMID 29100459, 2017). "Furthermore Liu and colleagues, through a screening using a high-throughput quantitative real-time miRNA PCR array, identified miR-524-5p as downregulated in BRAF mutated melanoma cells but not in wild-type BRAF cells." (PMID 28118616, 2017).
melanoma (continued). "Although ERK3 is known to be upregulated in multiple cancers and promotes cancer cell migration and invasion, the regulation of ERK3 expression in cancer cells is largely unknown except for one study showing the positive regulation of ERK3 by BRAF in melanoma cells." (PMID 28079973, 2017). "Targeting the MAP kinase pathway in patients with advanced melanoma was first attempted with sorafenib, either alone or in combination with chemotherapy with ultimately disappointing results 8, 9, 10, making it clear that more selective inhibitors of BRAF were needed." (PMID 28719152, 2017). "Indeed, it was found that NF1 suppression led to a 31-fold increase in resistance to PLX4720, as well as a partial (7-fold) resistance to MEK inhibition, demonstrating that human melanoma samples with innate resistance to BRAF inhibition and sensitivity to a MEK inhibitor harboured NF1 mutations." (PMID 28637487, 2017). "Non-V600 BRAF mutants may not be as responsive to BRAF inhibition based on BRAF-mutated melanoma data." (PMID 29034207, 2017). "Only MET and GAB1 exhibited significant induction following vemurafenib or PD0325901treatment, indicating this induction may contribute to the underlying mechanism of HGF rescue and explain the unique ability of HGF to rescue BRAF mutant melanoma cells from MAPK pathway inhibition." (PMID 28147313, 2017). "Indeed, they found in a zebrafish xenograft model that BRAF inhibitor‐pretreated melanoma cells, expressing elevated MITF levels, are not only more resistant to BRAF inhibition themselves, but also decrease the sensitivity to BRAF inhibition of untreated cells." (PMID 28694322, 2017). "Moreover, while the expression of these melanoma differentiation antigens was back to basal level in patients on progression, in a patient who then was treated with a BRAF/MEK inhibitor combination, the MITF target genes were again upregulated in response to treatment." (PMID 26977879, 2016). "In addition to BRAF inhibitors for melanoma, MEK inhibitors have also be developed." (PMID 27096871, 2016). "We demonstrate that 10 different melanoma cell lines regardless of their site of metastasis, BRAF mutation status or invasive behaviour in vitro, gain motility when transplanted into the trunk chicken microenvironment, reflecting the underlying plasticity of these cell types." (PMID 27172792, 2016). "Likewise, Held and colleagues reported that ~25% of BRAF-V600E melanomas are intrinsically resistant to vemurafenib in the context of normal PTEN and Rb expression, supporting the notion that loss of these tumor suppressors is not indispensable for intrinsic drug resistance." (PMID 27655717, 2016). "For example, while BRAF V600-mutated melanomas are sensitive to vemurafenib, BRAF V600-mutated colorectal cancers may not be as sensitive." (PMID 27191992, 2016). "To address the limitations of melanoma therapies, we included multiple tumor samples of patients relapsed from current treatments, with a diverse genetic background (with or without the common BRAF, NRAS or NF1 mutations) in these studies." (PMID 27829238, 2016). "CPI-17 was consistently and highly overexpressed (4 of 4) in melanoma samples containing neither oncogenic BRAF V600E nor oncogenic NRas Q61K/R mutations; suggesting that Ras activity may primarily be driven via the CPI-17-ERM pathway in these cells." (PMID 27793041, 2016). "Four out of ten melanomas had the BRAF V600E mutation and one a non-canonical BRAF D594N mutation." (PMID 27095580, 2016). "Molecular analysis confirmed a mutation in BRAF V600E in melanoma cells but not in CBN-like." (PMID 27313934, 2016). "Thus, sensitivity or resistance to the combination did not associate with mutant BRAF or NRAS status in melanoma cell lines." (PMID 27447557, 2016). "Patients with a superficial spreading melanoma, nodular melanoma, melanoma on a nevus, with a melanoma which is not classifiable or of unknown primary have a probability carrying a BRAF mutation of 63%." (PMID 27150060, 2016).
melanoma (continued). "Increased understanding of the key molecular events that drive melanoma development and progression has led to the development of targeted therapies to treat metastatic melanoma, such as small molecule inhibitors that block the mutant BRAF V600 kinase found in 40-50% of tumors." (PMID 27203220, 2016). "In addition to mutated BRAF, mutated NRAS accounts for about 20% of melanoma cases." (PMID 27941674, 2016). "However, which specific mutation is a precursor of the disease is still controversial since a number of studies concluded that the mutation of BRAF or NRAS genes are not specific for the progression of nevus to melanoma." (PMID 27313934, 2016). "However, comparisons between BRAF-mutant melanoma and CRC cell lines revealed that RAF inhibitors led to sustained suppression of mitogen-activated protein kinase (MAPK) signaling in melanoma cells, whereas CRCs exhibited only transient suppression of the pathway." (PMID 27308562, 2016). "Thus, RMD as well as other HDAC inhibitors may act as an endogenous regulator of Ras‐MAP kinase signaling in melanomas and may have high effectiveness in killing BRAF‐mutant cells." (PMID 27339860, 2016). "None of these 12 new primary melanomas harbored the BRAF V600 mutation." (PMID 27042173, 2016). "Importantly, evaluation of paired pre-treatment and on-treatment biopsies revealed that, despite inhibition of multiple pathway targets, the degree of MAPK inhibition achieved in patients with BRAF-mutant CRC is less than that observed in patients with melanoma treated with RAF inhibitor alone." (PMID 27308562, 2016). "Laboratory evidence suggests that reduced PDE5 expression triggered by BRAF activation increases the invasiveness and metastatic potential of melanoma cells; hence, pharmacological inhibition of PDE5 might have an unintended effect on melanoma risk." (PMID 27299522, 2016). "Thus, it could advance the field and provide the basis for further studies in BRAF inhibitor resistance in melanoma." (PMID 27448964, 2016). "Mutations in exon 15 of BRAF are not found, similar to human mucosal malignant melanoma." (PMID 29056717, 2016). "Interestingly, the EPHB6G404S mutation occurred significantly more frequently in melanomas without detectable BRAF or NRAS mutations." (PMID 27191502, 2016). "Moreover, the pattern of expression of the different ERβ isoforms was similar in BLM (NRAS-mutant, BRAF-wild type) and WM115 (BRAF V600D-mutant) melanoma cells: ERβ1 and ERβ5 were found to be expressed at similar levels while ERβ2 showed a higher level of expression." (PMID 27833586, 2016). "Moreover, we modeled the behavior of the malignant melanoma A375 cell line, harboring B-RAFV600E mutation, under the treatment of Dabrafenib, a commercial selective B-RAF inhibitor, recently approved in the treatment of patients with BRAF V600E mutation-positive advanced melanoma." (PMID 27015094, 2016). "Authors have demonstrated in melanomas wild type for NRAS and BRAF, that activating constitutively KIT mutations may be functionally equivalent to constitutive activation of the RAS-RAF-MEK-ERK pathway due to NRAS or BRAF." (PMID 26863566, 2016). "Thus, CRAF is a bona fide alternative oncogene for BRAF/NRAS/GNAQ/GNA11 wild type melanomas." (PMID 27273450, 2016). "Thus, in mutant BRAF human melanoma cells, it seemed plausible that this pathway could be involved in regulating melanoma cell clonogenicity." (PMID 27835901, 2016). "Finally, anti-VISTA reduced tumor-infiltrating MDSCs in the B16OVA and PTEN/BRAF melanoma models." (PMID 28031817, 2016). "In vitro studies demonstrate that ERβ ligands inhibit the proliferation of melanoma cells harboring the NRAS (but not the BRAF) mutation, suggesting that ERβ activation might impair melanoma development through the inhibition of the PI3K/Akt pathway." (PMID 27833586, 2016).